5S_rRNA (5S ribosomal RNA )
Gene: Ribosomal RNA gene on chromosome 2 (89,600,571 to 89,600,680, forward strand). Ensembl gene ENSG00000276861.
Gene Ontology:
Molecular function: structural constituent of ribosome
Cellular component: ribosome
Homologues: Orthologues: chimpanzee 5S_rRNA (100% identical). Paralogues in human: RNA5SP529 (100% identical), RNA5SP533 (100% identical), RNA5SP536 (71% identical), RNA5SP443 (70% identical), RNA5S1 (68% identical), RNA5S10 (68% identical), RNA5S11 (68% identical), RNA5S12 (68% identical), RNA5S13 (68% identical), RNA5S14 (68% identical), RNA5S15 (68% identical), RNA5S16 (68% identical), and 26 more.